FMOD (fibromodulin)
Diseases named in the same sentence as FMOD in open-access papers (continued):
Sharing a sentence is not in itself a finding about the gene and the disease.
Arthritis (1 paper, 2019). Inflammation of a joint. "Take advantage of the development of the Cre/Lox as well as CRISPR-Cas9 recombination system, the specific functions of FMOD during arthritis progression could be deciphered in detail with tissue-specific knockout animal models." (PMID 31920661, 2019). "FMOD-null (Fmod−/−) mice have distinct knee joints in comparison with their wildtype (WT) littermates at 36 weeks old, accompanied by a significantly higher histological arthritis score." (PMID 31920661, 2019). "Interestingly, FMOD is one of the small leucine-rich proteoglycans with the most significantly increased protein fragmentation in arthritis compared with macroscopically healthy articular cartilage from the age-matched donors." (PMID 31920661, 2019). "FMOD binds to collagens, and fragmentation of FMOD during arthritis progression may destabilize collagen fibrils, rendering them more susceptible to tissue collagenases." (PMID 31920661, 2019). "Furthermore, FMOD may participate in arthritis progression by directly manipulating inflammatory reactions." (PMID 31920661, 2019). "Therefore, arthritis progression may not only alter the degree and type of its carbohydrate substation but also lead to the breakage of the FMOD core protein." (PMID 31920661, 2019).
B-cell non-Hodgkin lymphoma (1 paper, 2022). The most common type of non-Hodgkin lymphoma. "Interestingly, a subset of the members in the SLRP protein family have been previously identified in B-cell Non-Hodgkin’s lymphomas including DCN, BGN, ASPN, FMOD, LUM, PRELP, and TSKU." (PMID 36873459, 2022).
brain tumors (1 paper, 2024). "Thus, FMOD has the potential to serve as a biomarker and at least in brain tumors, as a marker of disease severity." (PMID 39513108, 2024).
depression (1 paper, 2024). "FMOD exhibits potential as a therapeutic target for depression related to TBI, with its protective effects potentially mediated through the PI3K/AKT/mTOR signaling pathway." (PMID 38864941, 2024). "However, the role of Fibromodulin (FMOD) in TBI-related depression is not yet clear." (PMID 38864941, 2024).
diabetic cardiomyopathy (1 paper, 2025). Diabetic cardiomyopathy is a disorder of the heart muscle in people with diabetes. "Fibromodulin (Fmod) levels were higher in heart tissue of a diabetic cardiomyopathy (DCM) rat model, and in rat primary cardiac fibroblasts induced by high glucose, compared to the control group." (PMID 39592912, 2025).
dilated cardiomyopathy (1 paper, 2018). Cardiomyopathy which is characterized by dilation and contractile dysfunction of the left and right ventricles. "Our finding of increased FMOD levels in experimental and clinical HF is in line with recent bioinformatics data on differentially expressed genes in myocardial tissue from patients with hypertrophic and dilated cardiomyopathy." (PMID 30052659, 2018).
Hypertension (1 paper, 2023). The presence of chronic increased pressure in the systemic arterial system. "In this study, we examined FMOD expression in the myocardial tissues of rats with hypertension and AF." (PMID 37904680, 2023). "This indicates that hypertension was accompanied by AF‐induced cardiac fibrosis, whereas the downregulation of FMOD expression attenuated atrial fibrosis features in SHR‐AF." (PMID 37904680, 2023). "Thus, FMOD may be a promising therapeutic target for the treatment of spontaneous hypertension in patients with AF." (PMID 37904680, 2023).
Hypoglycemia (1 paper, 2016). A decreased concentration of glucose in the blood. "Moreover, we were able to point out several glycoproteins (Fibulin1, Versican, Fibromodulin) linked to the extracellular matrix (ECM), many crystallins and few solute carriers (Slc26a4, Slc6a13) whose expression was modified by hypoglycemia." (PMID 26918849, 2016).
injury (1 paper, 2024). Damage inflicted on the body as the direct or indirect result of an external force, with or without disruption of structural continuity. "Serum levels of FMOD were measured in patients with traumatic brain injury using qPCR." (PMID 38864941, 2024).
lymph node metastasis (1 paper, 2023). "In conclusion, FMOD overexpression is clinically associated with malignant progression and lymph node metastasis in OSCC patients." (PMID 37965134, 2023). "In this study, we identified that FMOD expression is overexpressed in OSCC and showed a significant association with clinical tumor stage (p = 0.011) and lymph node metastasis (p = 0.032)." (PMID 37965134, 2023). "Further analysis showed that FMOD expression was significantly correlated with lymph node metastasis (N0 and N1+N2) in OSCC patients (p = 0.032)." (PMID 37965134, 2023).
lymphedema (1 paper, 2025). Excess fluid collection in tissues, causing swelling. "Further expression analysis revealed that only four of these genes(POSTN, ASPN, FMOD, and MFAP5) exhibited statistically significant differential expression between lymphedema and control tissues, indicating their potential biological relevance in the fibrosis pathogenesis of lymphedema." (PMID 40881699, 2025).
myeloma (1 paper, 2022). "Critically, FMOD is not expressed in myeloma cells, suggesting that this protein does indeed come from the pBMAd cultures." (PMID 36713534, 2022).
neuroendocrine tumors (1 paper, 2020). "Among these, known biomarkers for MB (FSTL5), and other tumor types such as neuroendocrine tumors (ENO2, FMOD, ART3, COL6A3) and PIP, were found to be significantly up-regulated (dark green)." (PMID 32466393, 2020).
oral squamous cell carcinoma (1 paper, 2023). "However, the biological function of FMOD in oral squamous cell carcinoma (OSCC) remains largely unclear to date." (PMID 37965134, 2023).
osteoporosis (1 paper, 2020). A condition of reduced bone mass, with decreased cortical thickness and a decrease in the number and size of the trabeculae of cancellous bone (but normal chemical composition), resulting in increased fracture incidence. "Fibromodulin plays a role in bone mineralization, and its deficiency causes osteoporosis." (PMID 32917128, 2020).
pancreatic ductal adenocarcinoma (1 paper, 2021). An infiltrating adenocarcinoma that arises from the epithelial cells of the pancreas. "It encodes fibromodulin, an extracellular matrix protein overexpressed in pancreatic ductal adenocarcinoma." (PMID 33676569, 2021).
proliferative vitreoretinopathy (1 paper, 2018). Vitreoretinal membrane shrinkage or contraction secondary to the proliferation of primarily retinal pigment epithelial cells and glial cells, particularly fibrous astrocytes, followed by membrane formation. "The role of FMOD in initiation of proliferative vitreoretinopathy (PVR) has not been studied." (PMID 30298106, 2018).
retinal detachment (1 paper, 2021). An eye emergency condition which may lead to blindness if left untreated. "Another study also found that fibromodulin deficient mice presented with multiple areas of retinal detachment, suggesting that fibromodulin may be vital in the maintenance of retinal adhesion." (PMID 34298915, 2021). "Lumican and fibromodulin double knockout mice have shown several characteristics of high myopia, including increased axial length (10%) and retinal detachment (80%)." (PMID 34298915, 2021).
sarcopenia (1 paper, 2021). Progressive decline in muscle mass due to aging which results in decreased functional capacity of muscles. "Future studies are needed to elucidate the direct mechanism between FMOD and MSTN during human muscle aging for the management of sarcopenia." (PMID 34440852, 2021).
skin aging (1 paper, 2024). The gradual irreversible changes in structure of skin that occur as a result of the passage of time.. "Further research is necessary to elucidate the factors regulating FMOD in skin aging, especially because the regulation of FMOD may vary in different cells and tissues, or in different environments." (PMID 38706856, 2024). "In contrast, the expression of FMOD seems to be heterogeneous among reports of skin aging." (PMID 38706856, 2024).
tendinopathy (1 paper, 2023). "FMOD, as a key regulator of tendon strength and fibril maturation, has been shown to participate in tendinopathy pathogenesis." (PMID 37483637, 2023).
tumor (37 papers, 2013 to 2025). "Recent proteomic profiling of BC tissues shows that fibromodulin is one of the matrisome compounds enriched in metastatic lesions compared to primary tumours with associated ECM stiffening." (PMID 41463344, 2025). "Next, we investigated the cellular differentiation and angiogenesis in the tumors toward understanding the mechanism underlying reduced tumor growth in FMOD-silenced conditions." (PMID 35642785, 2022). "One of the proteins associated with dense extracellular matrices is fibromodulin, a collagen fibrillogenesis modulator expressed in tumor stroma but scarce in normal loose connective tissues." (PMID 28827814, 2017). "Fibromodulin is a small leucine-rich proteoglycan that plays a role in the regulation of collagen fibril assembly and has been implicated in various physiological processes, including tissue repair and tumor suppression." (PMID 39410926, 2024). "Fibromodulin, being a matrisome compound that is closely associated with collagens, is also an essential modulator of the interstitial fluid flux, stimulating a pressure gradient at the tumour/blood-tissue barrier and subsequently blocking the introduction of chemotherapy into the tumoural mass." (PMID 41463344, 2025). "In our bioinformatics analysis, we observed that OSMR and FMOD were mainly distributed in astrocytes in GBM tumor tissue, while IGFBP6 was predominantly found in NPC cells, all of which are crucial factors in GBM pathogenesis." (PMID 39815665, 2025). "To investigate the role of the five genes (OSMR, G0S2, IGFBP6, IGHG2, and FMOD) in specific cells within the tumor tissue of GBM patients, we illustrated the distribution of these genes across different cell types." (PMID 39815665, 2025). "Dysregulation of fibromodulin is a common cancer event, yet its impact on tumour fate remains complex, exhibiting both tumour-suppressive and pro-tumour properties that vary according to the cellular and molecular environment." (PMID 41463344, 2025). "In summary, the mRNA expression of OSMR, G0S2, IGHG2, and FMOD was significantly upregulated in tumor tissue of GBM patients compared to normal control tissue." (PMID 39815665, 2025). "The downregulation of FMOD suggests a weakening of the stromal barrier, potentially enabling tumor invasion." (PMID 40950184, 2025). "For example, significantly higher mRNA expression of FMOD was found in LK0412 tumor cells cocultured with 0861CAF and 1002CAF than in those cocultured with NOFs." (PMID 38822309, 2024). "In LK0923 tumor cells, FMOD, MMP1 and MMP9 were significantly upregulated after coculture with both 0836CAF and 1001CAF compared to tumor-matched CAFs." (PMID 38822309, 2024). "Our recently published data show that tumor-matched CAFs increased the mRNA expression of MMP1, MMP9 and FMOD in tumor cells when cocultured compared to tumor cells cultured alone in spheroids." (PMID 38822309, 2024). "Next, we investigated the mRNA expression of MMP1, MMP9 and FMOD in tumor cells after they were cocultured with different CAFs in 2D." (PMID 38822309, 2024). "Human CRC tissues had a higher expression of FMOD than the adjacent tissues that are more than 2 cm away from the tumor edge." (PMID 36986805, 2023). "The results showed that FMOD knockdown resulted in significant decreases in the tumor weight and volumes." (PMID 37965134, 2023). "More importantly, we confirmed the pro-tumor effects of FMOD in vivo using OSCC cells (CAL-27) xenograft in nude mice." (PMID 37965134, 2023). "We show an essential role of fibromodulin (FMOD) secreted by DGCs in promoting tumor angiogenesis via a crosstalk with endothelial cells." (PMID 35642785, 2022). "Consistent with our findings in tumor xenografts, FMOD depletion partially reduced VM in vitro, as noted by the decreased number of branches, junctions, meshes, and total tube length compared to control cells." (PMID 35737114, 2022).
tumor (continued). "We also found a similar expression pattern of CD133 and GFAP markers in small tumors formed under FMOD-silenced conditions in all three tumor models." (PMID 35642785, 2022). "Induction of a proliferative state at distant sites was associated with high levels of the stem-like/progenitor marker, SOX2, and required the upregulation of FMOD, an extracellular matrix component, which modulates tumor–stroma interactions." (PMID 35737114, 2022). "In line with our co-implantation experiments, we sought to define the importance of FMOD secreted by DGCs generated through a differentiation program initiated by GSCs during tumor growth in vivo using a syngenic intracranial glioma mouse model." (PMID 35642785, 2022). "Another small leucine-rich proteoglycan, fibromodulin (FMOD), was also upregulated at transcript level in tumor cells after coculturing with CAFs." (PMID 34283070, 2021). "A recent report emphasized that decreased FMOD expression inhibited tumor angiogenesis of SCLC by downregulating the angiogenic factors of ECs." (PMID 33234737, 2020). "It has been previously indicated that FMOD regulates collagen fibers in extracellular environment of tumor." (PMID 31198406, 2019). "These angiogenic regulatory effects strongly suggest that autocrine-secreted FMOD by cancer cells has a stimulating role in tumor angiogenesis of small-cell lung cancer." (PMID 31198406, 2019). "Overall, the question of the role of fibromodulin in tumor stroma is of potential clinical relevance as it affects the physiological barrier in solid tumors." (PMID 28827814, 2017). "We have previously shown that fibromodulin modulates collagen fibers in tumor extracellular environment." (PMID 28827814, 2017). "Our data suggest an important role of fibromodulin in the modulation of collagen fibrils in tumor stroma, and thus a role in accessibility of anti-cancer of drugs." (PMID 28827814, 2017). "Several proteins such as fibromodulin, CD229, MDM2, and CD23 have been recognized as tumor-associated antigens in CLL." (PMID 27302925, 2016). "Tumors grown in mice deficient in fibromodulin, a small leucine-rich protein important in organizing the collagen molecules into fibrils and fibers, resulted in lowered PIF and a loose tumor ECM." (PMID 26771643, 2016). "In most tumor types the tumor stroma is abundant in matrix PGs, particularly versican, lumican, and fibromodulin, and this suggests an important role of stromal PGs in controlling tumor progression." (PMID 24392351, 2013). "The possibility is therefore prospected that specific Fibromodulin-derived peptides may be exploited as tumour vaccines for the treatment of CLL-B, unless it would turn out that such peptides may evoke collateral cartilage-directed inflammatory reactions." (PMID 39980017, 2025). "Clinical studies have shown that high FMOD expression is closely related to tumor mortality, metastasis, and adverse events, and its expression level can be used as a potential biomarker for the risk of metastasis and immune escape ability in patients with cancer." (PMID 40881700, 2025). "Further studies indicated that the demethylation level of FMOD promoter might be related to its expression level in tumor cells and its role in inducing angiogenesis." (PMID 38331776, 2024). "The results of m6A sequencing and RNA sequencing showed that the EC could down-regulate the expression level of FMOD in tumor tissues, which might be related to the reduction of its m6A methylation modification regulatory enzyme METTL3." (PMID 38331776, 2024). "Furthermore, in LK0923 spheroids, increased expression of fibromodulin was found in LK0923/0836CAF spheroids compared to LK0923/tumor-matched CAFs." (PMID 38822309, 2024). "Recent studies have shown that FMOD acted as an angiogenic factor in tumor angiogenesis, which suggested that silencing FMOD might be a potential clinical therapy for anti-tumor." (PMID 38331776, 2024).
tumor (continued). "Thus, we also analyzed the mRNA expression of MMP1, MMP9 and FMOD in MACS-separated tumor cells that has been cocultured with tumor-matched and unmatched CAFs or NOFs for seven days." (PMID 38822309, 2024). "Additionally, the unmatched CAFs significantly upregulated the mRNA expression of MMP1, MMP9 and FMOD in tumor cells compared to tumor-matched CAFs." (PMID 38822309, 2024). "Briefly, METTL3 affected the stability of FMOD mRNA by regulating the m6A methylation modification of FMOD, thus affecting angiogenesis, which might interfere with the anti-tumor function of endostar combined with cisplatin." (PMID 38331776, 2024). "Notably, our finding highlights that FMOD was a direct target gene of miR-338-3p, which functioned as a tumor repressor in cancers, especially OSCC." (PMID 37965134, 2023). "Taken together, we herein the mapped the working model of pro-tumor role of FMOD in OSCC." (PMID 37965134, 2023). "Moreover, IHC assay using xenograft OSCC tumor showed that FMOD knockdown inhibited OSCC progression through suppressing EGFR/AKT or EGFR/ERK signaling axis." (PMID 37965134, 2023). "Taken together, these data suggested that FMOD had a clinically significant association with CRC progression and may promote CRC development by regulating tumor-associated immune cells." (PMID 36986805, 2023). "However, it enlightened us that DGC-secreted FMOD has some essential yet unidentified functions supporting GSC-initiated tumor growth." (PMID 35642785, 2022). "Interestingly, elevated FMOD levels were found in cranial lesions with a higher edema-to-tumor volume ratio by 3D modeling (t test, p = 0.02)." (PMID 35737114, 2022). "We demonstrate that DGC-secreted FMOD promotes tumor growth by inducing angiogenesis through integrin-dependent Notch signaling in endothelial cells, thus highlighting the importance of DGCs in tumor–stroma interactions that contribute to a sustainable niche for tumor growth." (PMID 35642785, 2022). "Finally, in an orthotopic intracranial GBM mouse model, we show that conditional silencing of FMOD in newly generated DGCs during tumor growth leads to a significant reduction of tumor growth." (PMID 35642785, 2022). "A similar trend was seen for cases with high tumor FMOD and SOX2 expression (p = 0.09)." (PMID 35737114, 2022). "There was a strong correlation between stroma and tumor FMOD expression (R = 0.78, p < 0.0001)." (PMID 35737114, 2022). "DGCs silenced for FMOD fail to cooperate with co-implanted GSCs to promote tumor growth." (PMID 35642785, 2022). "We propose a tumor evolution model, whereby GSCs, in addition to their self-renewal, continuously differentiate to form DGCs, which secrete protein factors like FMOD that mediate paracrine signaling in the different cell types of the tumor, thus creating a niche favorable to tumor growth." (PMID 35642785, 2022). "In fact, researchers have found that proteomic analysis identified typical tumor markers, including FSTL5, ART3, and FMOD, and revealed the prevalence of anti-inflammatory and tumor-promoting proteins that are characteristic of myeloid cells in CSF from patients with MB." (PMID 34977115, 2021). "Interestingly, two of the genes, MMP9 and FMOD, that both were upregulated in tumor cell/CAF spheroids compared to tumor spheroids were found to have a positive impact on overall survival in HNSCC patients." (PMID 34283070, 2021). "Moreover, FMOD involves in vasculature development and regeneration, tumor growth suppression and apoptosis prevention." (PMID 31198406, 2019). "Given that FMOD and other members of the proteoglycan family could be involved in collagen fibrillogenesis and cell adhesion and they also help to suppression of tumor growth, regulation of cytokine activity, and prevention of apoptosis." (PMID 31198406, 2019).